IL21R (interleukin 21 receptor)
Diseases named in the same sentence as IL21R in open-access papers (continued):
Sharing a sentence is not in itself a finding about the gene and the disease.
tendinopathy (1 paper, 2014). "IL-21R was mainly expressed by cells in the sublining layer and by cells within the extracellular matrix in the early tendinopathy group." (PMID 24757284, 2014). "Our study provides evidence that IL-21R is present in early tendinopathy and can be modulated in tenocytes by proinflammatory cytokines promoting the concept of IL-21R as inflammatory regulator in early tendon tissue damage." (PMID 24757284, 2014). "Herein we, demonstrate significantly increased IL-21R expression in early tendinopathy similar to that reported in RA and SSc suggesting an “activated” IL-21R+ tenocyte phenotype to be involved in the inflammatory milieu of early tendon disease." (PMID 24757284, 2014). "This project aimed to investigate the role and expression of the cytokine/receptor pair IL-21/IL-21R in human tendinopathy." (PMID 24757284, 2014). "We have previously reported increased levels of IL-15 in early tendinopathy, which shares common cytokine receptor γ-chain (γc), which is a functional component of the IL-21R complex." (PMID 24757284, 2014). "On the basis of these results we propose IL-21R as a potential inflammatory mediator in tendinopathy." (PMID 24757284, 2014). "Better understanding of the pathological cascade involving IL-21R could lead to the development of cell targeted treatment modalities in early human tendon disease." (PMID 24757284, 2014). "The purpose of this study was to investigate the presence and role of IL- 21 and IL-21R in human tendinopathy and was borne out of preliminary studies in animal and human models of tendinopathy in which the proinflammatory cytokines were found in increased levels." (PMID 24757284, 2014). "Secondly it may be that IL-21 expression occurs extremely early in the “tendinopathy spectrum” and that our cohort represents a later stage in the pathological process; however, we feel that the alternative ligand binding theory of IL-21R is a more likely scenario within tendinopathy pathology." (PMID 24757284, 2014). "Thus it may be that downstream activation of the IL-21R complex occurs in tendinopathy via IL-15 costimulation or alterative cytokine interactions." (PMID 24757284, 2014).
uveitis (1 paper, 2021). An inflammatory process affecting a part of or the entire uvea. "The effectiveness of anti-IL-21/IL-21R or downstream signals in uveitis may be confirmed in future studies." (PMID 33816637, 2021). "Although there is a distinct relationship between IL-21 and autoimmune uveitis, the biological agents that target IL-21 or IL-21R have not been tested in uveitis." (PMID 33816637, 2021).
viral myocarditis (1 paper, 2020). Myocarditis that is caused by an infection with a viral agent. "IL21R signaling plays a significant role in promoting follicular helper T (Tfh) cell-mediated cardiac injury in viral myocarditis (VMC) and response to chronic allograft nephropathy (CAN)." (PMID 32851066, 2020).
tumor (46 papers, 2010 to 2025). "Consist with the mouse and human clinical data, here we presented that IL-21R-deficient mice exhibited reduced numbers of spleen or liver/tumor IgA+ B cells and soluble IgA during MASH-driven hepatocarcinogenesis." (PMID 38720319, 2024). "MALAT1, as a sponge for miR-125a, regulates IL-21R signaling, participates in immune regulation of immune cells and tumor progression, and is a risk factor for survival and recurrence in GC." (PMID 35794986, 2022). "The increased/sustained expression of LEF-1 and IL-21R together with the enhanced effector capacity exhibited by Cbx3/HP1γ-deficient CD8+ effector T cells suggest they can persist to control tumor development." (PMID 34721405, 2021). "IL-21R expression is confined to the CD8+ T-cell effector population and its loss following deletion suggest that IL-21R function is essential to this population, which is critical for halting tumor development." (PMID 34721405, 2021). "We found that B/Mo/αGC vaccination restored the cytotoxic functions of Tim-3+PD-1+ NK cells in MHC class I-deficient tumours and that IL-21 was required for this process because the IL-21R blockade significantly abrogated the recovery of NK cell cytotoxicity." (PMID 28585539, 2017). "Per the IL21-IL21R axis, greater IL21R expression in tumor tissues from patients in the FinHER trial was associated with benefit of trastuzumab with regard to distant relapse." (PMID 29403144, 2017). "While the role of IL-21R signaling has been investigated in infectious and inflammatory diseases, unequivocal evidence about its possible contribution to tumor development in vivo is still poorly understood." (PMID 38720319, 2024). "Consistent with the previous results, compared with the Control group, MWA inhibited tumor growth, upregulated IL-21R expression on CD8 + T cells, CD4 + T cell, dendritic cells (DCs), and macrophages." (PMID 38833177, 2024). "We found that the TCR-T percentage in tumor-infiltrating lymphocytes was significantly higher in mice receiving IL-21R-TCR-T transfer than conventional TCR-T after cell transfer." (PMID 38643203, 2024). "(vi) Blockade of IL-21R signaling with an IL-21R blocking antibody induced tumor regression of MASH-driven HCC." (PMID 38720319, 2024). "The efficacy of engineered IL-21R within the orthotopic tumor model and other engineered T cell therapy needs further investigation." (PMID 38643203, 2024). "It has been reported that IL-21 produced by CD4+ T helper cells enhances the effector functions of CD8+ tumor-infiltrating lymphocytes (TILs) through IL-21/IL-21R signaling." (PMID 39338178, 2024). "Consistently, both triglyceride and cholesterol levels decreased in the serum and tumor tissue of Il21r−/− mice." (PMID 38720319, 2024). "To date, only one publication attempted to address the anti-tumor role of IL-21R in HCC development, particularly utilizing xenograft mouse models." (PMID 38720319, 2024). "In summary, our study revealed significantly decreased DNA methylation and elevated mRNA expression of IL21R in early-stage BC compared to benign tumours." (PMID 38723244, 2024). "In this study, we explored the impact of thermal ablation on IL-21R expression in tumor-infiltrating lymphocytes (TILs)." (PMID 38833177, 2024). "The expression levels of IgG, IgM, IgE, IgD, IgA, and IL21R on B cells from tumor samples were comparable to those from control samples." (PMID 38386050, 2024). "The weight and picture of tumors isolated at the end of the experiment also showed IL-21R-TCR-T treatment achieved better tumor control than conventional TCR-T." (PMID 38643203, 2024). "The percentage of Annexin V+ and 7-AAD+ population was lower in IL-21R-TCR-T than conventional TCR-T, suggesting that engineered IL-21R expression prevented the apoptosis of TCR-T during repetitive tumor antigen stimulation." (PMID 38643203, 2024).
tumor (continued). "Our results indicate that ablation promotes high expression of IL-21R by tumor-infiltrating immune cells, including T cells, macrophages, and DCs." (PMID 38833177, 2024). "AFP-TCR-T expressing a novel engineered IL-21R with constitutive IL-21 signal showed increased proliferation and tumor-infiltrating capacity, resistance to antigen-induced cell death, and superior antitumor function compared with conventional AFP-TCR-T." (PMID 38643203, 2024). "Increased numbers of IL21+ and IL26+ T cells have also been seen in PDAC and associate with an impaired clinical outcome, potentially through direct engagement with IL21R on tumor cells." (PMID 36689623, 2023). "The GEPIA results showed that the mRNA expression levels of USP18, IL2RA and IL21R were higher in tumor samples than in normal samples." (PMID 34001679, 2021). "The inability of Lef1-, Il21r-, Cbx3-Lef1- and Cbx3-Il21r-deficient CD8+ T cells to halt tumor development suggests that LEF-1 and IL-21R are necessary for their persistence in tumors." (PMID 34721405, 2021). "In the majority of patients (221/264), tumor cells expressed the receptor for IL-21 (IL-21R) and also a downstream target of IL-21, Blimp-1 (199/264)." (PMID 31540511, 2019). "High Blimp-1 expression, and concurrent high expression of both, IL-21R and its downstream target Blimp-1, were associated with poor survival of PDAC patients, implicating IL-21 in tumor progression." (PMID 31540511, 2019). "Further analyses revealed that the downregulation of the IL-21 serum level was correlated with an increased tumor stage of DLBCL, while the expression of IL-21R on the CD8+ T cells was positively correlated with the tumor stage." (PMID 24959288, 2014). "In addition, we utilized one-way ANOVA to compare IL21R methylation values of different subgroups of tumour subtype, tumour stage, tumour size, or lymph node involvement." (PMID 38723244, 2024). "Moreover, pro-inflammation cytokines, such as Il1b, Il12b and Il18, were upregulated in the tumor of Il21r−/− mice; whereas anti-inflammation cytokines, including Il10 and Il22 were decreased in the tumor of Il21r−/− mice." (PMID 38720319, 2024). "The transferred cells and TCR+ cells percentage in the bone marrow and spleen 7 days after transfer was comparable in mice receiving TCR-T and IL-21R-TCR-T, indicating that the powerful infiltrating capacity of IL-21R-TCR-T depends on the presence of tumor antigen." (PMID 38643203, 2024). "The proliferation of IL-21R-TCR-T after tumor stimulation was also monitored." (PMID 38643203, 2024). "However, the relationship between IL-21/IL-21R and IgA in liver or tumor microenvironment is unclear." (PMID 38720319, 2024). "Importantly, blockade of IL-21R signaling with an IL-21R blocking antibody induced tumor regression by enhancing cytotoxic CTL activation." (PMID 38720319, 2024). "To that end, we started to examine whether TA treatment regulates the expression of IL-21R on tumor-infiltrating immune cells." (PMID 38833177, 2024). "This suggests that ablation-induced anti-tumor effects may require the participation of the IL-21/IL-21R signaling pathway." (PMID 38833177, 2024). "Meanwhile, the PD-1 and TIM-3 expression and percentage of PD-1+TIM-3+ subsets were lower in CD8+ IL-21R-TCR-T than conventional TCR-T during repetitive coculture with HepG2, indicating that engineered IL-21R expression alleviated the exhaustion of TCR-T during repetitive tumor antigen stimulation." (PMID 38643203, 2024). "Therefore, CRA promotes B cell differentiation through the IL-21/IL-21R pathway and increases the affinity of anti-tumor antibodies." (PMID 37081540, 2023). "IL21R was highly expressed on a broad range of tumor-infiltrating immune cells, including CD4+ Tconv cells, T regulatory cells (Tregs), CD8+ T cells, B cells, NK cells, macrophages, monocytes, and dendritic cells (DCs) but minimally expressed in neutrophils and mast cells." (PMID 34869384, 2021).
tumor (continued). "We examined IL21R expression on immune cells in the tumor microenvironment (TME)." (PMID 34869384, 2021). "However, in the majority of tissues from PDAC patients, IL-21R was found on tumor cells, though to a varying degree, as were IL-21+ infiltrates." (PMID 31540511, 2019). "Moreover, there were fewer IFN-γ+ granzyme B+ antigen-specific CD8+ T cells from the tumours of Grail−/−Il21−/− mice compared to Grail−/− mice, supporting the role of IL-21R signalling in Grail−/− CD8+ T-cell expansion and function." (PMID 28798332, 2017). "Its activity, however, is dependent upon the expression of IL21R on the tumor cells." (PMID 26158860, 2015). "IL-21 might be captured by cells that express IL-21R — either tumor cells, as we demonstrated in this study, or Th17 cells themselves." (PMID 21949734, 2011). "The IL-17R was found in 93.8±10.2% of tumour cells, IL-21R in 36.7±7.6% and IL-22R in 27.7±9.5%." (PMID 20877351, 2010). "Furthermore, several lines of evidence indicate that IL-21R is involved in tumor immunity." (PMID 34721405, 2021). "However, the effects of IL21 on angiogenesis are complicated: in a tumor environment with abundant growth IL-21R activation was shown to be angiostatic, and IL-21 administration decreased tumor vascular density and tumor size in mice bearing EG7 tumor cells via STAT1 activation." (PMID 29358309, 2018). "Interestingly, bioinformatics-based analyses revealed that the IL21R exhibited the highest BC score within the activated NK cell gene network, indicating its importance within the genetic framework governing NK cell anti-tumor activity." (PMID 26470881, 2015). "Phenotypic analysis showed that IL-21R-TCR-T retained a less differentiated, exhausted and apoptotic phenotype than conventional TCR-T upon repetitive tumor antigen stimulation." (PMID 38643203, 2024). "IL-21R-TCR-T exhibited a less differentiated, exhausted and apoptotic phenotype than conventional TCR-T upon repetitive tumor antigen stimulation." (PMID 38643203, 2024). "Despite the impaired in vitro proliferation, our IL-21R enhanced the persistence of CD4+ TCR-T in vivo, which led to increased tumor-infiltrating cells." (PMID 38643203, 2024). "Along with human data on poor survival, advanced tumor stages and severe steatosis in HCC patients with high IL21R expression, our work implies that IL-21R plays a cancer-promoting role in MASH-driven HCC." (PMID 38720319, 2024). "TCR-T with the mutant IL-21 receptor (IL-21R-TCR-T) showed augmented proliferation capacity and killing function against high-load tumor antigens compared with conventional TCR-T in coculture assay and xenograft model." (PMID 38643203, 2024). "Interleukin-21 receptor (IL-21R) was reported to take part in JAK/STAT signaling pathway and can activate anti-tumor immunity, depress inflammation and tumor occurrence." (PMID 37988195, 2023). "Because IL-21R expression is induced and sustained in Cbx3/HP1γ-deficient CD8+ effector T cells without exogenous IL-21, we posit that whether IL-21 production is high or low during tumor development, it can still positively affect Cbx3/HP1γ-deficient CD8+ T-cell effector functions." (PMID 34721405, 2021). "Using this same Treg gating strategy, we next examined the surface expression of eight protein markers (CD30, OX40, 4-1BB, TIGIT, PD-L1, IL-1R2, IL-21R, and CCR8) on tumor-infiltrating Tregs of five CRC patients from our South-East Asian cohort." (PMID 33527196, 2021). "A comparison with a recently published list of cell-specific marker genes of tumor-infiltrating leukocytes (TILs) derived from pan-cancer data showed the presence of the B-cell marker FCRL2 and the natural killer cell marker IL21R." (PMID 33980253, 2021). "Tumor-infiltrating Tregs have been shown to exhibit a distinct signature comprising the co-stimulatory molecules (OX40, 4-1BB), cytokine receptors (IL1R2, IL21R, CCR8, CD30), and co-inhibitory molecules (PD-L1, TIGIT)." (PMID 33527196, 2021).
tumor (continued). "At the cellular level, USP18, TLR7, IL21R, GCNT1 and CHST7 were expressed in various tumor cell lines, while the expression of LHX2, IL2RA and IL5RA was low in CCLE." (PMID 34001679, 2021). "Removal of Cbx3/HP1γ restraint allows CD8+ T cells to become effector-like cells armed with an intrinsic heightened killing and persistence capacity to control tumor growth; LEF-1 function and IL-21R signaling are necessary." (PMID 34721405, 2021). "CpG 2006 has been shown to upregulate IL21R in B CLL cells, leading to enhanced IL-21-mediated apoptosis of the tumor cells." (PMID 26158860, 2015). "In the present study, an elevated level of IL-21R was observed on the peripheral CD8+ T cells in the DLBCL cases, and this positively correlated with the tumor grade." (PMID 24959288, 2014). "Moreover, mature FOXP3+ Tregs in the tumor express CXCR6, IL21R, IL1R1, IL18R1, and, to a lesser extent, CCR8." (PMID 40164596, 2025). "Consequently, the constitutive STAT3 signaling imparted by the engineered IL-21R induced a unique phenotypic alteration in IL-21R-TCR-T, resulting in a “long-lived effector” phenotype following tumor stimulation." (PMID 38643203, 2024). "The amounts of tumor-infiltrating CD8+ and CD4+ TCR-T were both higher in mice receiving IL-21R-TCR-T than conventional TCR-T, especially in the CD8+ TCR-T subsets with an approximately ten-fold increase in mice receiving IL-21R-TCR-T treatment." (PMID 38643203, 2024). "We found that the tumor growth was inhibited by both conventional TCR-T and IL-21R-TCR-T treatment and was persistently inhibited in mice receiving IL-21R-TCR-T, demonstrating the robust long-lasting in vivo antitumor efficacy of IL-21R-TCR-T." (PMID 38643203, 2024). "Even if our previous experiments have demonstrated the superior proliferation capacity of IL-21R-TCR-T upon CD3/CD28 activation, the proportion analysis supported by scRNA-seq data further revealed the phenotype of proliferating T cells after tumor antigen stimulation in detail." (PMID 38643203, 2024). "The percentage of CD4+ TCR-T subsets in mice peripheral blood was higher in IL-21R-TCR-T 7 and 14 days after transfer, indicating that the IL-21R promoted the persistence of CD4+ TCR-T, which led to the increased amounts of tumor-infiltrating CD4+ TCR-T cells." (PMID 38643203, 2024). "Second, rhIL-21 has a systemic profile and a high affinity for IL-21R, making it difficult to achieve effective enrichment at the tumor site; thus, safety and efficacy are not well balanced." (PMID 36936961, 2023). "Second, in mice, IL-21R signaling reduces accumulation of myeloid derived suppressor cells (MDSCs) in the TME to control rapid HCC growth and maintains an immunological memory response to tumor re-challenge." (PMID 34721405, 2021). "Notably, CRC tumor-infiltrating Tregs can be distinguished by the increased expression of a panel of signature markers, including CD30, IL1R2, IL21R, OX40, CCR8, PD-L1, TIGIT, and 4-1BB." (PMID 33527196, 2021). "IL-21R was found to be expressed on tumor cells of 221/264 patients and Blimp-1 in 199/264, but not in healthy pancreatic tissue." (PMID 31540511, 2019). "Mouse tumor epithelial cells do not express IL-21R, and stimulation of immortalized CRC cells derived from C57BL/6J mice with IL-21 does not affect cell growth and activation of STAT3/NF-kB." (PMID 25839161, 2015). "Besides, the tumor growth in mice that received CD34-TCR-T was comparable to conventional TCR-T, indicating that the constitutive IL-21 signal rather than CD34 ectodomain led to the superior antitumor function of IL-21R-TCR-T." (PMID 38643203, 2024). "Meanwhile, the percentage of CD8+ TCR-T rather than CD4+ TCR-T showed more increase within the tumor in mice receiving IL-21R-TCR-T than conventional TCR-T treatment, demonstrating the superior proliferation and infiltrating capacity of CD8+ IL-21R-TCR-T within the tumor microenvironment." (PMID 38643203, 2024).
tumor (continued). "Results from this study suggested that patients with CRC may harbor tumor-infiltrating Tregs with a specific protein signature, including the co-stimulatory molecules (OX40, 4-1BB), cytokine receptors (IL1R2, IL21R, CCR8, CD30), and co-inhibitory molecules (PD-L1, TIGIT)." (PMID 33527196, 2021). "However, tumour growth was comparable between WT and Il21−/− mice demonstrating that the effect seen in the Grail−/−Il21−/− and Grail−/− mice was due to the enhanced IL-21R signalling in the absence of Grail." (PMID 28798332, 2017). "Our data also suggest the essential role of IL-21R signalling in Grail−/− CD8+ T-cell function, since Grail−/− CD8+ T cells in the absence of IL-21 signalling expressed significantly low level of cytolytic cytokines and failed to suppress tumour growth." (PMID 28798332, 2017).